AFP (alpha fetoprotein)
Diseases named in the same sentence as AFP in open-access papers (continued):
Sharing a sentence is not in itself a finding about the gene and the disease.
tumor (continued). "KIF18A levels were found to be significantly related to clinicopathologic factors associated with alpha-fetoprotein (AFP) concentrations (≥200 ng/mL), tumor size (≥5 cm), clinical tumor-node-metastasis (TNM) stage, and portal vein tumor thrombus (PVTT)." (PMID 31392101, 2019). "In combined with sorafenib group, the patients had lower level of AFP (p=0.034), lower level of tumor size (p=0.043), and less type I/II PVTT (p=0.002)." (PMID 31467872, 2019). "In this cohort, those receiving high BED treatments tended to have smaller tumors, normal AFP, and earlier tumor stage than those who received low BED treatments." (PMID 30701703, 2019). "In contrast to that, cancer vaccines targeting individual tumor-associated antigens (TAAs), such as NY-ESO1, glypican-3 (GPC3), and alpha-fetoprotein (AFP), have met with limited success in HCC." (PMID 31816940, 2019). "Some factors are well accepted in previous reports, such as tumor size, portal vein invasion, and AFP level 16-18." (PMID 31598173, 2019). "CTC‐297N7.9 expression correlated with serum alpha‐fetal protein (AFP), tumor stage, and tumor differentiation." (PMID 31674731, 2019). "Others have demonstrated that serum AFP concentration is correlated with tumor size by bioluminescent and magnetic resonance imaging in a HepG2 orthotopic xenograft model." (PMID 31636665, 2019). "A lower preoperative LMR correlated with a high AFP concentration (P < 0·001), large tumour size (P < 0·001) and high rate of poorly differentiated HCC (P = 0·035)." (PMID 31388642, 2019). "Panels G-I show AFP expression in short term HCC patient of adjacent tissue < 1cm from tumor (G), tissue at operative site (H), and tumor tissue (I)." (PMID 30886700, 2019). "Serum AFP concentration prior to treatment was highly correlated with tumor size as established by bioluminescent imaging of the luciferase-expressing orthotopic tumors." (PMID 31636665, 2019). "Age, etiology, ALBI grade, AFP level, tumor type, portal vein invasion, type of EHM, and initial treatment modality were factors associated with overall survival in univariate analysis." (PMID 30845192, 2019). "Up to date, PIVKA-II has been employed as an alternative tumor marker of AFP for HCC diagnose including early HCC, with a cut-off value of 40 mAU/ml." (PMID 31114628, 2019). "On multivariable analysis, only pre-LT AFP, largest tumor size and tumor number were the preoperative predictors found to be associated with increasing the risk of post-LT HCC recurrence." (PMID 31752756, 2019). "When the cutoff was determined for the point on the ROC curve that maximizes sensitivity (70.0%) and specificity (76.1%) by Youden’s index, the optimal AFP cut-off value for tumor recurrence was 261.6 ng/mL [AUC = 0.730 (95% CI = 0.619–0.842); P < 0.001]." (PMID 31676847, 2019). "The only currently-accepted HCC tumour biomarker, alpha-fetoprotein (AFP), generally has suboptimal sensitivity and specificity for surveillance and diagnosis in most cases." (PMID 30781550, 2019). "Mortality was significantly correlated with serum albumin, primary tumor size, serum AFP, treatment modality, treatment method and treatment line." (PMID 31232945, 2019). "In HCC, three tumor markers, namely alpha-fetoprotein (AFP), AFP-L3, and des-gamma-carboxy prothrombin (DCP), have been used as serum biomarkers." (PMID 31718608, 2019). "In animals treated with 300 μCi of our conjugate, serum AFP levels decreased below pretreatment levels, indicating a reduction in tumor size." (PMID 31636665, 2019). "Several factors such as tumor size, insufficient safety margin, pretreatment AFP level, and ALT level had been reported as factors associated with LTP." (PMID 31311502, 2019). "In seven patents elevated tumor markers (AFP in three, HCG in two, LDH in two) were identified at the moment of relapse." (PMID 31597402, 2019).
tumor (continued). "On multivariate analysis, low BED, elevated AFP, larger tumor size, increased interval from diagnosis to SBRT, and low facility SBRT volume were associated with worse survival." (PMID 30701703, 2019). "AFP-high tumours show a distinct phenotype characterised by poor differentiation, enrichment of progenitor features and enhanced proliferation." (PMID 31285588, 2019). "We also found that hepatic expression of mRNA for AFP (an oncofetal protein and tumor marker) was significantly lower in the continuous canagliflozin group than in the vehicle group." (PMID 31652578, 2019). "In this cohort, the currently accepted tumour marker, AFP, was a poor discriminator of HCC with an AUC of 0.64 (95% CI 0.47–0.82, p = 0.065)." (PMID 30781550, 2019). "Apart from tumor size and number, markers like tumor differentiation, cancer-related symptoms and serum alpha-fetoprotein (AFP) levels are predictors of long-term post-OLT survival and can assist patient selection." (PMID 30909504, 2019). "They combined PLNPs (Eu2+- and Dy3+-doped Ca1.86Mg0.14ZnSi2O7) and gold nanoparticles (Ab-AuNPs) modified by α-fetoprotein (AFP) antibody for the detection of AFP in tumor cells." (PMID 31214570, 2019). "Because the value of AFP and tumor volume varied greatly, log transformation of AFP and tumor volume was performed to undergo Pearson’s correlation test." (PMID 30783140, 2019). "Morphological, biochemical, and histopathological examination as well as blood levels of the tumor marker, alpha-fetoprotein, in rats confirmed the curative effect of G4." (PMID 31847085, 2019). "The serum level of AFP showed close correlation with tumor differentiation and aggressiveness, and was also a suggested indicator, reflecting tumor doubling time." (PMID 31484287, 2019). "Overexpression of FBXO22 was detected in 61.8% (68/110) of HCC patients and was significantly correlated with serum AFP (p = 0.003), tumor size (p = 0.019), and vascular invasion (p = 0.031)." (PMID 30808376, 2019). "Expression of mRNA for AFP, an oncofetal protein that is used as a tumor marker, was significantly lower in the continuous canagliflozin group than in the vehicle group." (PMID 31652578, 2019). "The associations between sPD-L1/sPD-1 and AFP level, Child-Pugh score, tumor size, HBV history, BCLC stage, tumor number, grade of differentiation, microvascular invasion and capsular invasion were insignificant." (PMID 30506460, 2019). "High NAP1L1 expression was significantly associated with aggressive clinicopathologic features (i.e., serum AFP levels, larger tumor size, and late clinical stage)." (PMID 31516385, 2019). "In this study, we confirm the aberrant tumour overexpression of AFP in those patients with serum concentrations above 400 ng/ml and propose DNA methylation of its promoter as the driving mechanism of such overexpression." (PMID 31285588, 2019). "Antibiotic-treated Nlrp12-/- mice exhibited a profound reduction of tumor burden and expression of AFP after DEN-induced tumorigenesis." (PMID 30990169, 2019). "It was proposed that AFP and other secretory proteins formed immunosuppressive microenvironment and therefore enhanced tumor invasiveness and aggressiveness." (PMID 31915699, 2019). "Later, a phase I trial from Japan evaluated the role of anti-tumor vaccine using AFP-derived peptides in 15 patients with HCC." (PMID 31366113, 2019). "In clinical studies, tumor markers (such as α-fetoprotein, AFP), imaging, and histopathological biopsies are commonly used diagnostic methods for HCC." (PMID 31815633, 2019). "Biological features of the tumor (grading, microvascular or lymphatic invasion, alpha fetoprotein (AFP) level, and response to bridging therapies) also play an important role regarding HCC recurrence rates." (PMID 30729099, 2019). "With the stepwise addition of AFP, tumor number and combined treatment information, there was a small increase of C-statistic that was very close to the performance of the original model." (PMID 31777583, 2019).
tumor (continued). "On univariate survival analysis, serum AFP, tumor size, BCLC stage, TNM stage, differentiation, vascular invasion, and expression of FBXO22 were associated with OS." (PMID 30808376, 2019). "The level of AFP during patient-monitoring, however, can be difficult to interpret since elevated AFP can result from non-tumour liver activity, such as hepatotoxicity due to chemotherapy." (PMID 31652641, 2019). "A preoperative CTC (7.5 ml) of ≥2 is a novel predictor for tumor recurrence in HCC patients after surgery, especially in patient subgroups with AFP levels of ≤400 ng/mL or low tumor recurrence risk." (PMID 31269959, 2019). "PIVKA‐II, which is also referred to as des‐gamma‐carboxy prothrombin, is widely used as a tumor marker in addition to AFP for diagnosis of HCC." (PMID 31131509, 2019). "Nevertheless, we propose the VEGF ligands/receptors interplay (unbalanced in AFP-high tumours due to VEGFB/PGF overexpression) as a rationale for the enhanced activation of the VEGF pathway and thus the efficacy of ramucirumab in AFP-high HCC3." (PMID 31285588, 2019). "All these aggressive characteristics are in line with its known prognostic capacity and explain why the percentage of AFP > 400 ng/ml tumours increases with disease progression (from 9% in BCLC-A to 42% in BCLC-C)." (PMID 31285588, 2019). "In the univariable and multivariable analysis, the number of radiologic viable tumour ≤ 1, maximum diameter of viable tumour ≤ 1 cm, and AFP ≤ 20 ng/mL were independently predictive of PDS." (PMID 31316165, 2019). "Serum AFP concentration was measured in tumor-bearing mice at six weeks after HepG2-Red-FLuc orthotopic implantation." (PMID 31636665, 2019). "HCC screening is generally made by imagery techniques, such as ultrasound or computed tomography (limited to tumor bigger than 1 cm), or by assessing the alpha-fetoprotein (AFP) serum levels." (PMID 31258835, 2019). "Among all the clinical factors, alpha-fetoprotein (AFP) serum level and tumor differentiation were significantly associated with higher patient mortality." (PMID 30456450, 2019). "Univariable analysis revealed that the presence of SABR, ECOG 0–1, CP class A, single tumor, tumor size ≤8 cm, Vp3, AFP ≤200 ng/ml, prior treatment, and BED ≥65 Gy were predictors of superior OS." (PMID 31640728, 2019). "In our previous study, we established the MoRAL score, which is a simple and objective method of using serum tumor markers, AFP and PIVKA-II." (PMID 31484287, 2019). "On multivariate analysis, tumor size, tumor number, AFP level, PIVKA‐II level, presence of ascites, NLR, and ALBI grade were identified as prognostic factors with statistical significance." (PMID 31290618, 2019). "Specially, a panel of eight serum tumor markers (AFP, β‐HCG, CA125, CA15‐3, CA19‐9, CA242, CEA, and HE4) showed a good performance in prediction of BRCA1 mutation carriers (AUC = 0.974, Sensitivity = 0.714, Specificity = 1.000)." (PMID 30972954, 2019). "Factors significantly correlating with poor OS included AFP >300 and microvascular invasion on tumor explant." (PMID 31737675, 2019). "Subgroup analysis revealed that the patients younger than 60 years old, male patients, AFP more than 400ng/ml, tumor size more than 5cm, or type III/IV PVTT had OS benefits from TACE combined with sorafenib." (PMID 31467872, 2019). "Immunoblot analysis of tumour lysates showed that tumours developed from stem‐like HepG2SF1 cells had increased expression of AFP, CD133 and ALDH1A1 as well as upregulation of the Akt/mTOR axis and lower expression of pAMPK, AMPK, pACC and ACC." (PMID 30959553, 2019).
tumor (continued). "We examined the relationship between the VWF:Ag/ADAMTS13:AC ratio and serum tumor markers, such as AFP, DCP, and AFP-L3%." (PMID 31638892, 2019). "It has been suggested that alpha-fetoprotein (AFP) can be applied as a feasible tumor marker because its level was elevated in >90% of YST." (PMID 31114774, 2019). "The authors suggested using alpha-fetoprotein concentration and tumor size, among other criteria, as useful factors in selection of transplant-eligible patients with macrovascular invasion." (PMID 31163668, 2019). "The significant predictors of tumor recurrence were tumor number (p < 0.001), AFP (p = 0.001), Metroticket 2.0 (p < 0.001), AFP model (p < 0.001), TTV/AFP criteria (p < 0.001), and Warsaw criteria (p < 0.001)." (PMID 31520204, 2019). "Especially, the benefit of MDT management was greater in those with poor liver function, intermediate or advanced tumor stage or higher AFP levels." (PMID 30640924, 2019). "The decreased level of 5-hmC in HCC positively correlated with tumor size, AFP level and reduced overall survival, while a decreased level in non-tumor tissues was a prognostic factor the for early recurrence of HCC after surgical resection." (PMID 31060333, 2019). "Such factors include tumor factors (tumor number, size, location, and vascularity; portal vein invasion); patient factors such as age, Child–Pugh class, alpha-fetoprotein (AFP) level, and performance status have been also suggested as predictors." (PMID 30974843, 2019). "The levels of CEA, alpha-fetoprotein AFP, cancer and carbohydrate antigen CA tumor markers were significantly decreased (p < 0.00001) after DC-CIK treatment." (PMID 31484350, 2019). "Tumor size, tumor number, alpha‐fetoprotein, prothrombin induced by vitamin K absence‐II, lymphocyte count, albumin, and presence of ascites were adopted to construct the prognostic nomogram from the derivation cohort." (PMID 31290618, 2019). "On the other hand, the RB1 loss-of-function signature (designed to predict the absence of benefit to CDK4/6 inhibitors) was also a key characteristic of AFP-high tumours." (PMID 31285588, 2019). "It is reported that AFP level is related to tumor activity and play an important role in the diagnosis and prognosis of HCC patients." (PMID 31640620, 2019). "One unique aspect of our study is the Canadian HCC criteria for LT, which include AFP<400 ng/mL and a total tumor volume <115 cm3, which approximately equates one tumor approximately 6.1 cm in diameter or several smaller tumors." (PMID 30775356, 2019). "Pretreatment of Helicobacter hepaticus in transgenic mice aggravated tumor formation, with higher incidence, more tumor nodule and higher serum AFP." (PMID 31123503, 2019). "In this study, we reported that the expression of WISP3 was significantly decreased in HCC samples and reversely correlated with clinical features of HCC patients, such as AFP level and tumour size." (PMID 30793395, 2019). "Significantly bigger tumor size and higher alpha-fetoprotein secretion were found in HCCP than in HCCB." (PMID 31073374, 2019). "The HCC biomarker AFP similarly increased during disease progression in all of the mice, further illustrating comparable tumor growth." (PMID 31905933, 2019). "AACR-CCPW identifies a 1% tumor risk threshold and therefore recommends abdominal USS and AFP screening for all subtypes of BWSp." (PMID 32039119, 2019). "This decrease results in a reduction in preoperative AFP load, a more effective clearance of tumour cells from the blood and the prevention of tumour cell proliferation, which lead serum AFP levels to return to normal more quickly after surgery." (PMID 31822277, 2019). "Univariable analyses indicated that mean tumor size, AFP > 400 ng/mL, BCLC B and TACE-RFA was related to PFS." (PMID 31640620, 2019).
tumor (continued). "The correlation between WISP3 mRNA levels and pathological characteristics was analysed, and we found that the decreased level of WISP3 mRNA was correlated with larger tumour size and higher AFP level." (PMID 30793395, 2019). "Aside from uPA, our univariate analyses showed that the AFP level, tumor size, vascular invasion, and pathology stage were also significant prognostic factors associated with the OS of HCC patients undergoing curative resection." (PMID 31791275, 2019). "In the derivation cohort of our previous study, however, the maximal tumor size had been significantly associated with serum AFP, and the number and type of tumor with serum PIVKA-II, although those tumor factors had been associated with HCC recurrence." (PMID 31484287, 2019). "In the univariate analyses, preoperative alpha-fetoprotein (AFP) level >200 ng/ml, three MR imaging features (multifocal tumors, corona enhancement, and irregular tumor margin), and microvascular invasion (MVI) were associated with ER." (PMID 31850221, 2019). "In our study, survival was better in the TACE group; however the benefit disappeared after multivariable adjustment for age, etiology, ALBI grade, AFP level, tumor type, portal vein invasion, and type of EHM." (PMID 30845192, 2019). "Univariate and multivariate analysis revealed that AFP, tumor diameter, vascular invasion and cytokeratin-19/glypican-3 sub-typing were independent prognostic factors for RFS, thus comprised the risk scoring model." (PMID 31676847, 2019). "The expression levels of WISP3 were correlated with the pathologic characteristics of the patients, such as tumour size and AFP level." (PMID 30793395, 2019). "Due to local HCC listing criteria of total tumor volume and AFP, 60% (N=18/30) of HCV+/HCC patients were beyond Milan criteria at the time of LT." (PMID 30775356, 2019). "Of note, we noticed that MDT management was especially helpful for those with poor liver function, intermediate or advanced tumor stage or high AFP levels." (PMID 30640924, 2019). "An observational study showed that serum AFP progressively rose as the tumor grew over 5 cm in diameter." (PMID 31829979, 2019). "Significant differences were observed in the BMI, AST, ALB, TBIL, PT, APTT, and AFP levels, the antiviral therapy, tumor size, vascular invasion, metastasis, and BCLC Stages between the short‐ and long‐term survival groups." (PMID 31313476, 2019). "The results showed that AFP that decreased by less than 60% and tumour size that decreased by less than 50% after neoadjuvant chemotherapy were significant independent prognostic risk factors for 3-year RFS." (PMID 31822277, 2019). "Tumor markers were as follows: alpha fetoprotein (AFP) 0.46 ng/ml, human chorionic gonadotropin (hCG) < 1 mIU/ml, ferritin 152 ng/ml, neuron-specific enolase (NSE) 12.4 ng/ml, urinary vanillylmandelic acid (VMA) 7.82 mg/24 hours." (PMID 31060610, 2019). "In our orthotopic mouse model, we used serum AFP concentration as a corollary of tumor size, allowing a simple blood draw to track the response to treatment while animals were under radionuclide treatment." (PMID 31636665, 2019). "The results of the multivariate analysis showed that AFP decreased by less than 60% and tumour size decreased by less than 50% after neoadjuvant chemotherapy were significant independent prognostic risk factors." (PMID 31822277, 2019). "By analyzing the clinicopathological characteristics, we found that in addition to AFP level (P = .039), tumor stage (P = .037), and differentiation (P = .038), vascular invasion (P = .032) was also significantly associated with CTC‐297N7.9 expression." (PMID 31674731, 2019). "Univariate analysis showed albumin, bilirubin, GGT, ALT, prothrombin time, AFP, tumor size of the largest nodule, and combined treatment to be statistically significant factors affecting survival." (PMID 31777583, 2019).